IL15 (interleukin 15)
Diseases named in the same sentence as IL15 in open-access papers (continued):
Sharing a sentence is not in itself a finding about the gene and the disease.
pulmonary fibrosis (7 papers, 2019 to 2025). Chronic progressive interstitial lung disorder characterized by the replacement of the lung tissue by connective tissue, leading to progressive dyspnea, respiratory failure, or right heart failure. "Moreover, the classical WNT/β-catenin pathway regulates inflammatory cytokines (TNF, IL-1, IL-6, IL-8, and IL-15), which play important roles in reducing lung inflammation and pulmonary fibrosis and are linked to the pathogenesis of BPD." (PMID 37180448, 2023). "Mechanistically, the IL-15 antifibrotic role was associated with the induction of interferon-γ-responsive invariant natural killer T (iNKT) cells or T-helper cell type 17 suppressor RORγ+ Treg cells in chronic pancreatitis models and in allergen lung fibrosis models respectively." (PMID 34769128, 2021). "It was shown that higher IL-15 production was associated with high SPAP levels and pulmonary fibrosis." (PMID 40299554, 2025). "Some enriched pathways of interest included Leukocyte extravasation signaling, IL-15 production, and Pulmonary Fibrosis Idiopathic Signaling Pathway." (PMID 38168374, 2023). "Enriched pathways of interest include Pulmonary Fibrosis Idiopathic Signaling Pathway, IL-8 Signaling, and IL-15 Production." (PMID 38168374, 2023). "Although primarily associated with maintaining lymphocyte homeostasis and chronic inflammation, IL-15 has been recently proposed as a potential anti-fibrotic agent in mouse models of interstitial pulmonary fibrosis and pancreatic fibrosis." (PMID 31882598, 2019). "Indeed, IL-15 reverses fibrosis by modulating inflammation by recruiting Foxp3+ Treg cells such as in lung fibrosis but also by reducing the levels of profibrotic cytokines such as TGF-β and by blunting fibroblasts transformation into myofibroblasts." (PMID 34769128, 2021). "Alternatively IL-15 could counteract TGF-β1-induced fibroblast-to-myofibroblast differentiation as reported in a pulmonary fibrosis model." (PMID 31360169, 2019). "Moreover, IL-15 counteracts TGF-β1-induced myofibroblast differentiation in human fetal lung fibroblasts and could exert antifibrotic effects in certain forms of pulmonary fibrosis." (PMID 31360169, 2019).
sarcoidosis (7 papers, 2012 to 2025). Sarcoidosis is a multisystemic disorder of unknown cause characterized by the formation of immune granulomas in involved organs. "We also found that the activity of other cytokines including GM-CSF (JAK2), IL-15 (JAK1/3), IL-6 (JAK1/2), IL-12 (JAK2/TYK2) and TNF (JAK-independent) are also evident in sarcoidosis." (PMID 35668129, 2022). "Several proteins were identified with higher abundance in BAL of sarcoidosis patients, including cadherin 5 (CDH5), transferrin (TF), C-C motif chemokine 24 (CCL24), interleukin 15 (IL15) apolipoprotein A (LPA) and mitochondrial superoxide dismutase (SOD2)." (PMID 27259755, 2016).
type 2 diabetes (7 papers, 2016 to 2025). "IL-15 is involved in skeletal muscle growth and is closely related to obesity and type II diabetes." (PMID 28025491, 2016). "In a prior investigation, a negative association between plasma IL-15 and fat mass was found, independent of the diagnosis of type 2 diabetes, which suggests that IL-15 may be involved in the regulation of body fat mass." (PMID 29791651, 2018). "Despite limitations, this study demonstrates a distinctive inflammatory tear cytokine profile (elevated IL-6, CXCL8, IL-15, CCL5, VEGF) in type 2 diabetes patients, contrasting with decreased systemic inflammation." (PMID 41030257, 2025).
ulcerative colitis (7 papers, 2016 to 2025). An inflammatory bowel disease involving the mucosal surface of the large intestine and rectum. "It is implied that regulation of memory T cell differentiation through intervention with IL-7, IL-15, and IL-21 is an effective measure for the treatment of ulcerative colitis." (PMID 33597887, 2020). "More specifically, Nishiwaki and co-workers found an increased expression of mRNA of both IL-15 and IL-15Rα receptor in the mucosal tissues of IBD patients, especially in subjects with ulcerative colitis." (PMID 28797042, 2017).
acute GVHD (6 papers, 2012 to 2026). "Donor-derived IL-15 is instrumental in the development of acute GVHD following allogeneic bone marrow transplantation (BMT), as it significantly exacerbates tissue inflammation in both the gut and liver." (PMID 40943537, 2025). "The 180-day cumulative incidence of grade II–IV acute GVHD was 24% in patients with day 7 IL-15 levels>median (12.5 pg/mL) versus 28% in patients with day 7 IL-15 levels ≤ median (P = 0.8)." (PMID 23437070, 2013). "TGF-β has been reported to restrain acute GVHD, while the response to IL-7 and IL-15 (in the lymphopenic setting induced during bone marrow transplantation) exacerbates GVHD." (PMID 22879925, 2012). "Similarly, the 180-day cumulative incidence of grade II–IV acute GVHD was 25% in patients with day 14 IL-15 levels>median (10.5 pg/mL) versus 33% in patients with day 14 IL-15 levels ≤ median (P = 0.8)." (PMID 23437070, 2013). "Differential expression analysis showed that low levels of IL18-R1, LIF-R and IL22-RA1 were seen in patients who subsequently developed acute graft versus host disease (AGvHD) whilst lower levels of CD244, TSLP, IL15-RA and IL-33 were observed in patients who developed chronic GvHD." (PMID 38235129, 2023). "In the current study, we did not observe any association between levels of IL-7 or IL-15 early after allo-HSCT and grade II–IV acute GVHD." (PMID 23437070, 2013). "Importantly, IL-7 and IL-15 levels on days 7 or 14 after transplantation did not predict grade II–IV acute GVHD." (PMID 23437070, 2013). "In summary, these data suggest that IL-7 and IL-15 levels remain relatively low after nonmyeloablative transplantation, and that IL-7 and IL-15 levels early after nonmyeloablative transplantation do not predict for acute GVHD." (PMID 23437070, 2013).
AIDS (6 papers, 2012 to 2023). A syndrome resulting from the acquired deficiency of cellular immunity caused by the human immunodeficiency virus (HIV). "Currently, IL-15 and some of its derivatives, such as IL-15 super-agonists, are in clinical trials for cancer and AIDS." (PMID 38149252, 2023). "Several studies have shown that IL-15 production is compromised in AIDS patients, and supplementation of IL-15 improves the function of immune cells from these patients in vitro." (PMID 22958464, 2012). "In addition, adoptive NK cells were tested together with the IL-15 superagonist ALT-803, which has already been demonstrated to promote NK cell function in vitro and in vivo in patients suffering from acquired immune deficiency syndrome (AIDS) (NCT03899480)." (PMID 33807011, 2021). "Macaques treated with IL-15 during acute SIV exhibited a 1000-fold increase in viral load set point in chronic infection and accelerated progression to AIDS." (PMID 34578331, 2021). "When RMs underwent IL-15 blockade during primary or chronic SIV infection, SIV replication and disease progression were comparable to control groups, suggesting IL-15 is not solely responsible for increased viremia or progression to AIDS." (PMID 34578331, 2021).
brain tumors (6 papers, 2015 to 2023). "Early results, however, have not revealed significant efficacy for prolonging survival in patients with brain tumors through the use various cytokines, including IL-2 and IL-15." (PMID 38002466, 2023). "This antigen-specific response was further amplified in patients with brain tumor upon conditioning of whole blood with IL-2/IL-15/IL-21." (PMID 29970101, 2018). "We therefore concluded that the mesothelin-specific response of patients with grade IV brain tumors has potential to be enhanced with IL-2/IL-15/IL-21 conditioning." (PMID 29113296, 2017). "We also report IL-15 secretion by brain tumour cells in vivo and in vitro." (PMID 26183281, 2015). "Moreover, they support the hypothesis of a therapeutic usage of IL-15, administered alone or in combination with IL-15Ra, in brain tumors." (PMID 29286001, 2017). "In the reanalysis, we found that patients with grade IV brain tumour (GBM), constituting the majority of group of the study cohort, exhibited a significantly increased IFN-γ response to MPF and mesothelin precursor peptide pool if the PBMCS were conditioned with IL-2/IL-15/IL-21." (PMID 29113296, 2017).
breast tumor (6 papers, 2015 to 2025). "Increased expression of myeloid TRIB2 reduces IL-15 levels in breast tumors, resulting in reduced numbers of T cells that are key to the antitumor immune responses." (PMID 39376611, 2024). "A close relationship of increased IL-15 levels in patients with a Grade 3 breast tumor and those with the poorest survival outcome were moreover confirmed." (PMID 32929618, 2021). "To determine if exposure to these 3 cytokines simultaneously would affect the ability of NK cells to kill breast tumor cells, we isolated NK cells from human PBMCs and stimulated them in an IL-15/IL-12/IL-18 rich environment for 16 hours." (PMID 25879689, 2015). "Lastly, we confirmed that when human NK cells were exposed to a similar cytokine environment as was observed in IL-15 TG/MT tumors, they were capable of killing human breast tumor cells." (PMID 25879689, 2015). "Overall, NK cells found within IL-15 TG/MT tumors are likely more capable of killing breast tumor cells than those found in MT tumors." (PMID 25879689, 2015). "IL-15 overexpression in MT breast tumors created an environment where several cytokines that affect NK cell activation and proliferation were altered." (PMID 25879689, 2015). "Studies have shown that both overexpression and knockdown of TRIB1 in myeloid cells promote the growth of breast tumors in mice; myeloid TRIB1 is a negative regulator of the antitumor cytokine IL-15." (PMID 39376611, 2024).
capillary leak syndrome (6 papers, 2016 to 2025). A syndrome characterized by leakage of intravascular fluids into the extravascular space. "Compared to IL-2, the use of IL-15 minimizes capillary leak syndromes and has less side effects overall, thus providing a strong rationale to use IL-15 instead of IL-2." (PMID 28620386, 2017).
endothelial dysfunction (6 papers, 2019 to 2026). In vascular diseases, endothelial dysfunction is a systemic pathological state of the endothelium (the inner lining of blood vessels) and can be broadly defined as an imbalance between vasodilating and vasoconstricting substances produced by (or acting on) the endothelium. "Other pathogenic effects of IL-17A on endothelial dysfunction include the induction of the gene expression of chemokines and pro-inflammatory mediators, including IL-8, CCL20, IL-6 and IL-15." (PMID 33322218, 2020). "IPA analysis revealed that immune-inflammatory pathways (e.g., IL-15 signaling, complement system, leukocyte extravasation) and biological processes related to vascular permeability, endothelial dysfunction, and immune dysregulation were significantly enriched in HAE." (PMID 41484981, 2026). "These increased levels of IL-15 may contribute to endothelial dysfunction during PE." (PMID 31721933, 2019). "Here we propose a model in which CX3CR1+ CD8 T cells promote endothelial dysfunction by the combined effects of CX3CL1, IL-15, and TNF." (PMID 32976527, 2020). "Supporting our model, we demonstrate increased expression of CX3CL1 and IL-15 in human atherosclerotic plaques and in the aortic endothelium of SIV/SHIV-infected RM, reflecting microenvironments that sustain endothelial dysfunction." (PMID 32976527, 2020).
eosinophilia (6 papers, 2014 to 2025). "The cytokines such as IL-4, IL-5, and IL-13 are released causing eosinophilia and the pro-inflammatory cytokines like IFN-γ, TNF, IL-6, and IL-15 are increased promoting systemic inflammation." (PMID 41229508, 2025). "Treatment with anti-IL-17 was able to attenuate eosinophilia and IL-15 and, consequently, led to improvement in AHR." (PMID 37965351, 2023). "As a consequence IL-15 may be a cytokine that plays a key role in the eosinophilia found in BP patients." (PMID 30837635, 2019).
experimental autoimmune encephalomyelitis (6 papers, 2012 to 2023). An autoimmune demyelinating disease of the central nervous system that is produced experimentally in animals by the injection of homogenized brain or spinal cord in Freund's adjuvant. "In contrast, IL-15 protected against nephrotoxic serum nephritis and experimental autoimmune encephalomyelitis." (PMID 23028657, 2012). "A neuroprotective role of IL-15 is suggested by the increased motor neuron death in knockout mice lacking the IL-15 receptor α (IL15Rα), and by the ability of IL-15 treatment to ameliorate the symptoms of the experimental autoimmune encephalomyelitis (EAE)." (PMID 31533339, 2019). "However, there are still documents, which demonstrated that IL-15 is beneficial to experimental autoimmune encephalomyelitis." (PMID 29616032, 2018). "Conversely, IL15 has anti-apoptotic and neurotrophic effects, due to its ability to suppress nitric oxide in neurons, which can be one of the components responsible for its protective effects in experimental autoimmune encephalomyelitis." (PMID 26441851, 2015).
graft versus host disease (6 papers, 2016 to 2024). An immune system disorder that occurs after allogeneic hematopoietic stem cell transplant and is a reaction of donor immune cells against host tissues. "Because NK expansion protocols frequently include factors such as high-dose IL-2, IL-15, and IL-21 that also stimulate proliferation of T cells, graft-versus-host disease is a particular concern." (PMID 29456538, 2018). "It has also been shown that increased levels of IL-15 significantly decrease PD-1 expression by T-cells and compromise self-tolerance following allo-SCT, potentially increasing the risk of graft versus host disease (GVHD)." (PMID 37190240, 2023). "These Hu-NSG-Tg(IL-15) mice demonstrate robust and long-term reconstitution with human immune cells, but do not develop graft-versus-host disease (GVHD), allowing for long-term studies of human NK cells." (PMID 36851579, 2023). "However, higher base line or peak serum IL-15 levels are also related to severe toxicity, such as cytokine release syndrome (CRS), graft-versus-host disease (GVHD), and neurotoxicity." (PMID 36167591, 2022).
head and neck cancer (6 papers, 2021 to 2025). A primary or metastatic malignant neoplasm affecting the head and neck. "For instance, a combination therapy of CTLA-4 inhibitor (Ipilimumab), CIML NK cell infusion, and interleukin-15 superagonist (N-803) is currently being evaluated for the treatment of advanced head and neck cancer (Clinical trials." (PMID 36932395, 2023). "The phase II clinical trial NCT04847466, referred above, is currently recruiting patients with recurrent/metastatic gastric or head and neck cancer, to test PD-L1 CAR-NK in combination with Pembrolizumab, together with an IL-15 superagonist." (PMID 40519903, 2025).
Hepatic steatosis (6 papers, 2018 to 2025). Steatosis is a term used to denote lipid accumulation within hepatocytes. "Beyond its role in immunology, IL-15 is involved in muscle metabolism, contributing to fat loss, improved insulin sensitivity, and reduced hepatic steatosis." (PMID 41301428, 2025). "Sun and Liu found that transfer of the IL-15 gene in high-fat diet-induced obese mice prevented weight gain, lessened the development of hepatic steatosis, and improved glucose homeostasis." (PMID 34861815, 2021).
liver cancer (6 papers, 2019 to 2025). An epithelial or non-epithelial malignant neoplasm that arises from the liver. "Another research on Interleukin-15-armored GPC3-CAR T cells for solid tumors, including liver cancer, showed that IL15 increases the expansion, intratumoral survival, and antitumor activity of GPC3-CAR-T cells in patients." (PMID 40308592, 2025). "NKG2D-CAR-T co-expressing CX3CR1 reduces tumor burden and extends survival in a liver cancer model, compared with control T cells or IL-15-overexpressing NKG2D CAR-Ts." (PMID 40612946, 2025).
mesothelioma (6 papers, 2021 to 2025). A usually malignant and aggressive neoplasm of the mesothelium which is often associated with exposure to asbestos. "On the basis of those findings, it is possible that IL-15-deficient mice might show an increased incidence of mesothelioma following exposure to asbestos." (PMID 33874885, 2021). "Future investigations concerning IL-15 gene expression and signaling upon exposure to asbestos and the effect of IL-15 deficiency on mesothelioma using in vitro and in vivo experiments should provide critical information of the relationship between IL-15 and mesothelioma caused by asbestos." (PMID 33874885, 2021). "There is some preclinical data suggesting IL-15 may be useful in combination with an anti-PDL-1 antibody to activate NK cells against mesothelioma targets." (PMID 37296902, 2023). "Several lines of evidence suggest that NK cells may play a role in the tumor microenvironment, with asbestos inhibiting the cytolytic activity of NK cells and some data indicating that IL-15 in combination with an anti-PDL-1 antibody may be effective in re-activating NK cells against mesothelioma." (PMID 37296902, 2023). "Administration of IL-15 superagonist and glucocorticoid-induced tumor necrosis factor receptor–related protein (GITR) agonist alongside RT improved control of irradiated AE17 mesothelioma tumor." (PMID 36387076, 2022).
metastatic cancer (6 papers, 2020 to 2022). A carcinoma which has spread from the original site of growth to another anatomic site. "We have produced heterodimeric IL-15 (hetIL-15), which has shown anti-tumor efficacy in several murine cancer models and is being evaluated in clinical trials for metastatic cancers." (PMID 36713398, 2022). "Infusion of IL-15 (2 μg/kg/d) into metastatic cancer patients led to greater than 350-fold expansion of CD56bright NK cells that had enhanced tumor recognition, cytokine production, and cytotoxic activity." (PMID 34372571, 2021). "However, this treatment strategy is associated with severe toxicity in patients, i.e., a first-in-human clinical trial in which patients with metastatic cancer were treated with recombinant IL-15 showed significant toxicity at the effective treatment dose." (PMID 34681717, 2021). "Finally, we summarize the clinical applications of IL-2 and IL-15 in metastatic cancer." (PMID 33266177, 2020).
myelodysplastic syndrome (6 papers, 2016 to 2023). A clonal hematopoietic disorder characterized by dysplasia and ineffective hematopoiesis in one or more of the hematopoietic cell lines. "By now, IL-15 activated CIK cells have been licensed as an advanced medicinal product for patients with high-risk leukemia and myelodysplastic syndrome (ATMP § 4b Abs." (PMID 27620209, 2016). "We and others have previously shown that IL-15 stimulated CIK cells are a promising immunotherapeutic approach for the treatment of patients with impending relapse following allogeneic SCT for acute leukemia or myelodysplastic syndrome." (PMID 27620209, 2016). "Additionally, in both primary myelofibrosis (PMF) and myelodysplastic syndromes (MDS), higher levels of IL-15 were detected." (PMID 37153603, 2023). "Other studies have shown clinical efficacy of treatments with allogeneic NK cells activated with IL-25 or stimulated with IL-15, IL-12, and IL-186 in AML or myelodysplastic syndrome (MDS) patients." (PMID 33665226, 2021). "A trifunctional molecule combining IL-15 with CD16 and CD33 engagers has also been constructed to support NK cell response in myelodysplastic syndrome (MDS)." (PMID 32272610, 2020).